VEGFC (vascular endothelial growth factor C)
Diseases named in the same sentence as VEGFC in open-access papers (continued):
Sharing a sentence is not in itself a finding about the gene and the disease.
lymph node metastasis (135 papers, 1999 to 2025). "Mechanically, it has been reported that intratumoral expression of the vascular endothelial growth factor C (VEGF-C) is highly associated with lymph node metastasis." (PMID 40778224, 2025). "Activation of mTOR pathway was shown to be associated with increased LVD and lymph node metastasis via upregulation of VEGFC in various cancers in in vitro and in vivo models and in human samples." (PMID 33128283, 2021). "VEGFC is an integral part of lymphangiogenesis and has been associated with lymph node metastases and prognosis in a variety of malignancies." (PMID 24999452, 2014). "In order to know whether c‐Myc activation is associated with lymph node metastasis in pNET, we evaluated the effect of c‐Myc on VEGFC expression in pNET cells (QGP‐1 and NIT‐1)." (PMID 33128283, 2021). "The overexpression of the lymphangiogenic factors VEGFC and VEGFD, activators of VEGFR3, has been associated with lymph node metastasis and poor outcome in BC patients." (PMID 36835014, 2023). "Here, we identified an exosomal lncRNA (lncAKR1C2) that was clinically correlated with lymph node metastasis in gastric cancer in a VEGFC-independent manner." (PMID 37903800, 2023). "VEGFC is a member of VEGF family and its increased expression is associated with lymph node metastasis in PCa specimens." (PMID 33509203, 2021). "Vascular endothelial growth factor C (VEGFC) is a determinant of lymphatic vessel density, tumor staging, and lymph node metastasis, and is associated with the failure of nasopharyngeal carcinoma to respond to radiotherapy." (PMID 33095808, 2020). "Further study indicated that HUMT exerted its function by recruiting YBX1 protein to the promoter region of FOXK1 and promoted its transcription, activating lymph node metastasis-related Akt/mTOR/VEGFC signaling." (PMID 32138762, 2020). "In terms of lymphatic metastasis, molecules including USP7, FAK, as well as the VEGFC-VEGFR3 interaction, are shown to associate with incidence of lymph node metastases of ovarian cancer." (PMID 31888563, 2019). "That research group went on to demonstrate that COX-2 causes upregulation of vascular endothelial growth factor C (VEGF-C) expression and encourages growth of new lymph vessels and subsequent lymph node metastasis." (PMID 30248985, 2018). "Targeting VEGFC/VEGFR-3 pathway for lymph node metastasis and reducing the incidence of distant organ metastases have been given a therapeutic approach." (PMID 27145366, 2016). "A positive association between vascular endothelial growth factor-C (VEGF-C) expression and lymph node metastasis has been reported in several cancers." (PMID 16755294, 2006). "Vascular endothelial growth factor-C expression and lymph node metastasis were independent prognostic factors for 5-year survival on multivariate analysis (odds ratio (OR) 9.10, P=0.0272 and OR 8.52, P=0.0322, respectively)." (PMID 12888807, 2003). "Vascular endothelial growth factor-C mRNA and immunohistochemically detected tissue expression of the protein in gastric cancer correlate with lymphatic invasion and lymph node metastasis and in some studies, venous invasion with reduced survival." (PMID 12888807, 2003). "Vascular endothelial growth factor C (VEGF-C), interleukin-4 (IL-4), colony-stimulating factor 2 (CSF2), prospero homeobox 1 (PROX1), and TEK receptor Tyrosine Kinase (TEK) is significantly associated with lymph node metastasis in renal cell carcinoma (RCC)." (PMID 38167072, 2024). "High expression levels of STAT3 in invasive breast cancer correlates with lymph node metastases, VEGFC/D, and VEGFR3 expression; therefore, STAT3 may play an indirect role in promoting lymphangiogenesis during involution." (PMID 38218743, 2024). "Furthermore, in metastatic lymph nodes, the vascular endothelial growth factor C (VEGF-C) overexpression is closely correlated with the lymph node metastasis of NSCLC." (PMID 30364292, 2018).
lymph node metastasis (continued). "Interestingly, our data also revealed that the serum protein level of VEGFC was significantly higher in advanced patients and patient with lymph node metastasis." (PMID 30131072, 2018). "Numerous studies have shown a significant correlation between levels of the lymphangiogenic vascular endothelial growth factor C (VEGF-C), lymphatic vessel invasion, lymph node metastasis and/or overall survival." (PMID 20698997, 2010). "Vegf-C and lymphatic vessel density (LVD) are related to lymph node metastasis (LNM) and poor prognosis of patients in GC, and serum vascular endothelial growth factor-C (SVegf-C) has been recently proposed as a useful biomarker for LNM and prognosis in GC." (PMID 19412438, 2007). "High VEGFC levels may reflect an increased capacity for distant metastasis, as suggested by studies in other cancers, which have shown that VEGFC and VEGFR-3 expression correlate with lymph node metastasis and poor outcomes." (PMID 41333209, 2025). "One of the factors with the highest capacity to promote lymphangiogenesis is the vascular endothelial growth factor-C (VEGF-C), which appears overexpressed in many carcinoma models, correlating with the tumor lymphangiogenesis and the appearance of lymph node metastasis." (PMID 35565388, 2022). "Moreover, a large number of clinical studies have shown the correlation between tumor expression of VEGFC or VEGF-D and lymph node metastasis." (PMID 27145366, 2016). "Nevertheless, studies involving tumors of several organs have suggested that high expression of the prolymphangiogenic factor vascular endothelial growth factor-C (VEGF-C) and high intratumoral or peritumoral lymph vessel density (LVD) are correlated with lymph node metastasis and poor prognosis." (PMID 27486768, 2016).
gastric cancer (102 papers, 2003 to 2026). A primary or metastatic malignant neoplasm involving the stomach. "High expression of VEGFC is significantly associated with poor prognosis in various malignancies, including lung cancer, gastric cancer, thyroid cancer, colorectal cancer, and HNSCC." (PMID 36203528, 2022). "SOAT1 also induces the expression of SREBP1 and SREBP2, which further enhance the level of VEGFC and ultimately contribute to invasion in gastric cancer." (PMID 37304239, 2023). "VEGFR3 expression was reported in many types of human cancers including colorectal and gastric cancers, which often co express VEGFC giving opportunity for autocrine regulation of signaling and growth promotion." (PMID 35681695, 2022). "Overexpression of miRNA-27b inhibited the proliferation, migration, and tube formation of HUVECs and decreased angiogenesis in colorectal cancer and gastric cancer via inhibiting VEGFC/VEGFR2 signaling." (PMID 35453336, 2022). "Our further investigation showed that avasimibe significantly decreased the expression and secretion of VEGFC in gastric cancer cells." (PMID 34790132, 2021). "SAM administration promoted VEGFC promoter methylation and downregulated its expression in gastric cancer cells." (PMID 33170152, 2020). "Vascular endothelial growth factor C (VEGFC) plays a prominent role in the lymphatic metastasis of many cancers, including gastric cancer, cervical cancer, melanoma, and thyroid cancer." (PMID 29717026, 2018). "It has been proposed that PELI2 could promote the growth and metastasis of gastric cancer cells by regulating vascular endothelial growth factor C, considered as a sensitive predictive tool for lymphatic metastasis in gastric cancer." (PMID 40500708, 2025). "VEGFC expression was positively correlated with glioma and stomach cancer." (PMID 37852616, 2023). "Furthermore, SOAT1 induced SREBP1 and SREBP2 expression participated in the pro-lymphangiogenic process via promoting VEGFC expression and ultimately contributed to gastric cancer lymphangiogenesis." (PMID 34790132, 2021). "VEGFC expression has previously been shown to predict melanoma patient survival, and its expression has been shown to be regulated by DNA methylation in gastric cancer." (PMID 31069961, 2019). "In addition, micro RNAs (miR27b, miR‐101, and miR‐128) have been shown to downregulate VEGFC expression and lead to the suppression of tumor growth, metastasis, invasion, migration, and angiogenesis in gastric cancer, bladder cancer, and hepatocellular carcinoma." (PMID 33128283, 2021). "A significant upregulation of vascular endothelial growth factor C (VEGF-C) by RhoGDIβ in human gastric tumor tissues, as well as parental gastric cancer cell lines, was observed." (PMID 40710299, 2025). "The expression of VEGFC and VEGFD correlates with recurrence in head and neck squamous cell carcinomas and lymphatic metastases in gastric cancer, respectively." (PMID 37852616, 2023). "Through the reciprocal effects of VEGFC and CCL5, CRIP1 can promote lymphangiogenesis and lymphatic metastasis development in gastric cancer." (PMID 37409440, 2023). "In gastric cancer, we found CTHRC1 was highly co-expressed with many factors, such as ACVRL1, ANGPTL3, ANGPTL4, NOTCH4, VEGFB, VEGFC etc., which have been proved to play an important role in angiogenesis in various cancer." (PMID 35928443, 2022). "SAM treatment induces DNA hypermethylation at the promoter of vascular endothelial growth factor-C (VEGF-C) and subsequently reduces VEGF-C expression, which inhibits gastric cancer cell growth and tumorigenesis." (PMID 30283496, 2018). "Herein, we report that an exo-lncRNA (ENST00000604184, termed lncAKR1C2 because it shares the same maternal gene as AKR1C2) was upregulated in the serum of gastric cancer patients with LNM, and was positively related to lymphatic vessel density in a VEGFC-independent manner." (PMID 37903800, 2023).
gastric cancer (continued). "The pro-metastatic role of TANs via lymphangiogenesis is nevertheless observed in multiple cancers—gastric cancer (CD15+ TANs correlate with nodal metastasis), bladder cancer (circDHTKD1/CXCL5/VEGFC axis; ETV4-CXCL1/8-MMP9/VEGFA axis), and now LUAD (CCL15-CCR1-VEGFC)." (PMID 40739091, 2025).
lymphedema (97 papers, 2007 to 2025). Excess fluid collection in tissues, causing swelling. "Herein, nucleoside-modified mRNA-LNPs encoding murine VEGFC were utilized to stimulate lymphatic growth and function and reduce experimental lymphedema in mice." (PMID 34103491, 2021). "Here, we utilized nucleoside-modified mRNA encapsulated in lipid nanoparticles (LNPs) encoding murine Vascular Endothelial Growth Factor C (VEGFC) to stimulate lymphatic growth and function and reduce experimental lymphedema in mouse models." (PMID 34103491, 2021). "These are the only reports of patients with mutations in VEGFC (Lymphedema, hereditary, ID, [MIM 615907] or congenital primary lymphedema of Gordon)." (PMID 30071673, 2018). "Further studies are required to fully understand the biochemical interactions between the proteins in the VEGFR3/VEGFC signaling axis and their role in causing primary lymphedema." (PMID 30071673, 2018). "In humans, loss-of-function mutations in either VEGFC or VEGFR3 can lead to lymphedema." (PMID 41214597, 2025). "Although the detailed mechanism by which VLNT alleviates lymphedema remains incompletely understood, recent literature increasingly supports lymphangiogenesis mediated by vascular endothelial growth factor C (VEGF‐C)." (PMID 40066947, 2025). "Several research examining the preclinical animal model of acquired lymphedema provide evidence for therapeutic lymphangiogenesis through the activation of VEGFC/VEGFR-3 signaling pathways." (PMID 39633684, 2024). "Experimental treatments of lymphedema have centred around delivery of lymphangiogenic growth factor such as vascular endothelial growth factor‐C (VEGF‐C); however, these efforts have been largely abandoned due to equivocal outcomes in clinical trials." (PMID 35652284, 2022). "Animal models of lymphedema have also demonstrated that inflammation-induced CD4+ T cells stimulate vascular endothelial growth factor C (VEGF-C) expression." (PMID 35743063, 2022). "Alterations of the VEGFR3 signaling pathway are a common feature of primary lymphedema, and supplementation with VEGFC-releasing patches or administration of HGF or ANG-2 improves the lymphedema condition, at least in animal models." (PMID 36612017, 2022). "This event positively correlated with lymphedema, the number of macrophages and the expression of VEGFC measured two- and eight-weeks post-radiation." (PMID 36612017, 2022). "These experiments revealed that the administration of VEGFC mRNA-LNPs effectively reduced paw thickness and clinical score in the experimental secondary lymphedema mouse model compared to the Poly(C) RNA-LNP control treatment." (PMID 34103491, 2021). "Ketoprofen, a non-steroid anti-inflammatory drug, reduced tail volumes in mice with acquired lymphedema by promoting VEGFC-induced lymphangiogenesis." (PMID 34579131, 2021). "Here, the authors show that delivery of nucleoside-modified Vascular Endothelial Growth Factor C (VEGFC) mRNA, encapsulated in lipid nanoparticles, induces organ-specific lymphatic growth and reverses experimental lymphedema." (PMID 34103491, 2021). "In particular, overexpression of VEGFC resulted in lymphedema exacerbation accompanied by higher immune cell infiltration and vascular leakage in a mouse model." (PMID 34579131, 2021). "Further studies (e.g., in large animal models) will be needed to develop the most efficient treatment strategies and protocols to cure secondary lymphedema utilizing the nucleoside-modified VEGFC mRNA-LNP platform." (PMID 34103491, 2021). "Fourth, and most importantly, the nucleoside-modified VEGFC mRNA-LNP platform proved to be effective in reversing disease progression in an experimental secondary lymphedema mouse model by inducing the formation of a functional lymphatic network." (PMID 34103491, 2021).
lymphedema (continued). "Research on potential pharmacologic agents such as vascular endothelial growth factor C (VEGF-C), stem cells, and 9-cis retinoic acid (alitretinoin), show great promise in lymphedema reduction in other animal models of the disease." (PMID 31797883, 2019). "Hereditary human lymphedema conditions involving the vascular endothelial growth factor C (VEGF-C)/VEGF receptor 3 (VEGFR-3) signaling pathway." (PMID 29484295, 2018). "Additionally, recombinant VEGFC application can stimulate robust lymphangiogenesis in adults, suggesting its therapeutic potential in managing conditions such as lymphedema and tissue repair." (PMID 41214597, 2025). "Additionally, there is an increase in vascular endothelial growth factor C (VEGF-C) in lymphedema tissue, primarily secreted by macrophages." (PMID 40759794, 2025). "In addition, Huynh and colleagues have identified a connection between a heterozygous deletion of the VEGFC gene in the 4q34.3 region of the chromosome and a Milroy-like lymphedema condition." (PMID 40041256, 2023). "Th2 cells aggravate lymphedema by augmenting tissue fibrosis, whereas Th1 and Th17 cells promote non-productive lymphangiogenesis and exacerbate lymphedema by enhancing macrophage VEGFC production." (PMID 35450048, 2022). "Mutations in vascular endothelial growth factor C (VEGFC) and vascular endothelial growth factor receptor 3 (VEGFR3) induce altered lymph formation, which may progress to lymphedema." (PMID 34579131, 2021). "These important results demonstrate that administration of a single low-dose of VEGFC mRNA-LNPs is an efficient strategy to induce the formation of functional lymphatic vessels, which then reverse the development and progression of secondary lymphedema." (PMID 34103491, 2021). "(2009) demonstrated that the ameliorative effect of VEGFC augmentation is evident in the murine model through the positive microvascular remodelling that characterizes the lymphoedema in that model, and by its clear resolution following exogenous VEGFC administration." (PMID 30746892, 2019). "VEGFC, which is a gene encoding the ligand for the vascular endothelial growth factor receptor 3 (VEGFR3/FLT4) and important for lymph vessel development during lymphangiogenesis, has been associated with a specific subtype of primary lymphedema." (PMID 30071673, 2018). "There were also reports of reduced penetrance since six individuals carrying a VEGFC mutation had no clinical signs of primary lymphedema (n = 4) or reported occasional swelling (n = 2) of feet and ankles." (PMID 30071673, 2018). "Therefore, VEGFC is an important therapeutic target to induce lymphatic regeneration in lymphedema." (PMID 34103491, 2021). "Linsitinib restricted enlargement of small lymphatics and tissue swelling during lymphedema development, likely by inhibiting IGF1R-driven vascular endothelial growth factor-C (VEGF-C) synthesis by macrophages." (PMID 40060910, 2025). "VEGFC and PROX1 play key roles in lymphangiogenesis and lymphatic endothelial identity, with therapeutic potential for lymphedema and tissue repair, respectively." (PMID 41214597, 2025). "Upregulation of vascular endothelial growth factor C (VEGF‐C) and podoplanin was observed in the VLNT and lymphedema groups in comparison to the control group." (PMID 36176614, 2022). "The study finds a correlation between Th17 cell expansion and lymphedema in filarial infections, proposing that increased Th17 responses may stimulate VEGF-C (Vascular Endothelial Growth Factor C) production, thereby driving the development of pathology." (PMID 40137708, 2025). "Taken together, our results indicate that nucleoside-modified VEGFC mRNA-LNP treatment reverses experimental lymphedema in a validated mouse model without showing any adverse events in the experimental animals." (PMID 34103491, 2021). "Importantly, the VEGFC mRNA-LNP treatment reverses secondary experimental lymphedema without showing any obvious adverse events in an animal model." (PMID 34103491, 2021).
lymphedema (continued). "Importantly, VEGFC mRNA-LNP treatment reversed experimental lymphedema by restoring lymphatic function without inducing any obvious adverse events." (PMID 34103491, 2021). "To provide proof-of-concept and test whether nucleoside-modified VEGFC mRNA-LNP treatment influences disease progression in an experimental lymphedema system, we assessed the present platform in a recently developed Diphtheria toxin-inducible genetic secondary lymphedema mouse model." (PMID 34103491, 2021). "This situation may be expected in non-syndromic lymphedema, since only VEGFC/VEGFR3 axis genes that have been identified as the sole source of the disorder, yet 64% of patients with familial history and 92% of patients with sporadic non-syndromic lymphedema do not harbor these mutations." (PMID 25383712, 2014).